ENSG00000284626 (novel protein)
Gene: Protein-coding gene on chromosome 15 (90,234,200 to 90,265,462, forward strand). Ensembl gene ENSG00000284626.
Genetic constraint (gnomAD): Missense variants: 326 observed, 375.42 expected, observed/expected ratio (o/e) 0.87, 90% interval 0.79 to 0.95. Synonymous variants: 156 observed, 160.45 expected, observed/expected ratio (o/e) 0.97, 90% interval 0.85 to 1.11.